KRT13 (keratin 13)
Diseases named in the same sentence as KRT13 in open-access papers (continued):
Sharing a sentence is not in itself a finding about the gene and the disease.
prostate carcinoma (6 papers, 2016 to 2023). A carcinoma that arises from epithelial cells of the prostate gland. "We previously reported that KRT13 overexpression in prostate cancer cells was associated with stemness gene expression, including c-Myc." (PMID 35078507, 2022). "To understand the underlying molecular basis of how KRT13 reprograms prostate cancer bone and brain metastases, we adopted LNCaP as the model for more extensive gene expression profiling analyses." (PMID 27835867, 2016). "Collectively our data demonstrate that KRT13 expression is associated with poor prognosis at multiple stages of disease progression and may represent an important biomarker of adverse outcome in patients with prostate cancer." (PMID 27711225, 2016). "On the other hand, KRT13-overexpressing prostate cancer cell lines are reported to be highly migratory, with high expression of genes related to the epithelial-mesenchymal transition and CSCs." (PMID 36610719, 2023). "Another study showed that KRT13 expression is increased in the tumor zone with a higher degree of stemness in prostate cancer." (PMID 36610719, 2023). "We previously reported that KRT13 promotes prostate cancer bone and brain metastases through RANKL-independent pathways by an undefined mechanism." (PMID 35078507, 2022). "Dysregulated KRT13 expression was found in carcinomas of the tongue, head and neck, uterine cervix, mouth, ovary, breast, bladder cancer, esophageal cancer, and prostate cancer." (PMID 35078507, 2022). "In contrast to our results, a study in 2016 revealed a correlation between KRT13 tissue expression and prostate cancer metastasis." (PMID 35267445, 2022). "This communication delineates the potential functional role of KRT13 in human prostate cancer growth, development, progression, and metastasis." (PMID 27835867, 2016). "We examined KRT13 protein expression in three lineage-related isogenic human prostate cancer bone metastatic cell models, LNCaP/C4-2B, ARCaPE/ARCaPBM, and PC-3/PC-3M." (PMID 27835867, 2016). "The pathophysiologic significance of these results is supported by clinical specimens in which more intense KRT13 expression was observed in human prostate cancer bone metastasis, and in human breast and lung cancer bone and brain metastases." (PMID 27835867, 2016). "Because aggressive and therapeutic resistant prostate cancer cells often express stem cell-associated genes, we tested the possible directive effects of KRT13 in driving prostate cancer local growth, invasion and distant metastasis." (PMID 27835867, 2016). "In this study, we focused on defining the potential functional roles of KRT13 in prostate cancer progression and metastasis for four reasons." (PMID 27835867, 2016). "Increased KRT13 expression also correlates significantly with castration resistance, bone metastasis, and Gleason grade of prostate cancer patients." (PMID 27835867, 2016). "We evaluated the overall incidence of bone, brain, and soft tissue metastases in mice (N ranged from 8 to 18/group for neo-control or KRT13-transduced prostate cancer cells)." (PMID 27835867, 2016). "In our study, we observed KRT13 consistently increased cell proliferation, migration and invasion of all three prostate cancer cell lines, but these cells expressed variable levels of genes associated with EMT, stemness and neuroendocrine (NE) phenotype." (PMID 27835867, 2016). "When KRT13 expression was determined at a single cell level in primary tumor tissues of 44 prostate cancer cases, KRT13 level predicted bone metastasis and the overall survival of prostate cancer patients." (PMID 27835867, 2016). "We examined the basal levels of KRT13 expression in developing human prostate and in three lineage-related isogenic prostate cancer bone metastatic progression cell models, and validated KRT13 expression in an aggressive and metastatic CWR22Rv1 model." (PMID 27835867, 2016).
prostate carcinoma (continued). "We reported previously that forced KRT13 expression drove prostate cancer metastasis through a RANKL-independent mechanism, although RANKL-mediated signal network was shown to be associated with EMT, stemness, neuroendocrine or neuromimicry, osteomimicry and tumor cell bone colonization." (PMID 35078507, 2022). "We previously reported that KRT13 induced prostate cancer progression and metastasis." (PMID 35078507, 2022). "A detailed comparative study of KRT13 function between breast and prostate cancer is warranted." (PMID 35078507, 2022). "KRT13 promoted bone and brain metastases of human prostate cancer." (PMID 33197880, 2020). "While lower levels of KRT13 expression were associated with the basal and luminal epithelial cell compartments of the adult normal and benign hyperplastic prostate glands, elevated KRT13 expression, in comparison, was found in invasive human prostate cancer cells." (PMID 27835867, 2016). "Differential expression of genes in KRT13-transfected prostate cancer cells confirmed the altered expression of epithelial-to-mesenchymal transition (EMT)-, stemness-, neuroendocrine-/neuromimicry-, osteomimicry-, develop- mental- and extracellular matrix-related genes." (PMID 27835867, 2016). "We hypothesized that KRT13-positive prostate cancer cells could displace the “guarding” megakaryocytes and gain access to bone and soft tissue microenvironments." (PMID 27835867, 2016). "It is possible that benign KRT13+ epithelial cells serve as cells of origin for prostate cancer." (PMID 27711225, 2016). "These comparisons allowed us draw the following conclusions: 1) There are remarkable similarities between KRT13- and RANKL-expressing prostate cancer cells; both of these cells share common genes associated with survival-, EMT-, stemness-, neuroendocrine-, and developmental phenotypes." (PMID 27835867, 2016). "We established the following correlative observations supporting the idea that KRT13 could have a functional role in prostate cancer metastases." (PMID 27835867, 2016). "Employing prostate cancer cell QDL in a cohort of well-defined primary prostate cancer tissue specimens collected from 44 hormone-naïve patients, we demonstrated that KRT13 expression, at a single cell level, correlates with the overall survival of prostate cancer patients." (PMID 27835867, 2016). "We observed increased KRT13 expression in some prostate cancer cell lines as they become progressively more aggressive with the potential of increasing bone-homing capability, but by contrast aggressive 22Rv1 cells capable of metastasizing to bone and brain expressed very low levels of KRT13." (PMID 27835867, 2016). "Thus, in this study we tested the hypothesis that KRT13 expression could alter the homing potential of prostate cancer cells to secondary organ sites." (PMID 27835867, 2016). "We report here that cytokeratin 13 (KRT13), an intermediate filament protein, plays a directive role in prostate cancer bone, brain, and soft tissue metastases." (PMID 27835867, 2016). "In the context of our previous report where we demonstrated prostate cancer bone and soft tissue metastases can be promoted by RANKL, here we show KRT13 reprograms prostate cancer bone and brain metastases occurred in a RANKL-independent manner." (PMID 27835867, 2016). "Examination of a rare prostate tissue specimen retrieved at autopsy from a patient who died of prostate cancer, following treatment with radiation therapy and ADT revealed residual KRT13+ cells lining ducts/acini." (PMID 27711225, 2016). "In summary, we established the first robust human prostate cancer bone and brain metastatic model with forced expression of KRT13 in the indolent non-metastatic LNCaP cell line." (PMID 27835867, 2016). "These contrasting collagen expression profiles in KRT13- and RANKL-expressing LNCaP cells could play a role in anchor prostate cancer cells in the brain microenvironment." (PMID 27835867, 2016).
epithelial dysplasia (5 papers, 2017 to 2024). "Gain of keratin 17 expression and loss of keratin 13 were significantly observed in differentiated epithelial dysplasia." (PMID 38891785, 2024). "A high CD163+ MΦ number showed significantly positive associations with the degrees of epithelial dysplasia, abnormal Ki‐67 expression and cytokeratin 13 (CK13) loss in TL tissues." (PMID 31890299, 2019). "Recent studies investigated the use of keratin 13 (CK13) and keratin 17 (CK17) as indicative markers associated with usual/classic and differentiated epithelial dysplasia, in that dysplastic lesions show a decreased expression of CK13 and an increased expression of CK17." (PMID 31896811, 2020).
oral epithelial dysplasia (4 papers, 2017 to 2022). "Recently, the diagnostic utility of the immunohistochemical markers cytokeratin 13 (CK13) and cytokeratin 17 (CK17) has been established for oral epithelial dysplasia." (PMID 30187167, 2018).
pterygium (4 papers, 2020 to 2025). A wedge-shaped fibrovascular lesion arising from the bulbar conjunctiva and extending to the cornea. "Specific forms of keratin, including keratin 13 and 4, are increased in pterygium and have a role in cell migration." (PMID 34707671, 2021). "KRT13 mRNA expression was significantly higher in EBMD, SND, and pterygium (p ≤ 0.018), and FABP5 was increased in pterygium samples (p = 0.007)." (PMID 40094891, 2025). "Since EBMD, SND and pterygium lead to changes in the corneal epithelium, we analyzed levels of the corneal keratins KRT3 and KRT12, as well as the conjunctival keratin 13 (KRT13) in our samples." (PMID 40094891, 2025). "Among keratins, a significantly increased KRT13 mRNA expression in conjunctival IC samples was noticeable in EBMD, SND, and pterygium patients." (PMID 40094891, 2025). "In this context, we compared the expression of corneal keratins KRT3, KRT12, and KRT13 in EBMD, SND, and pterygium." (PMID 40094891, 2025). "KRT13 mRNA expression was significantly higher in EBMD, SND, and pterygium IC samples than in controls (p = 0.05; p = 0.001; p = 0.018)." (PMID 40094891, 2025).
esophageal squamous cell carcinoma (3 papers, 2016 to 2023). Esophageal squamous cell carcinoma (ESCC) is a type of esophageal carcinoma (EC) that can affect any part of the esophagus, but is usually located in the upper or middle third. "KRT13 is transcriptionally up-regulated by KLF4 to induce differentiation of esophageal squamous cell carcinoma." (PMID 36949761, 2023). "Lower KRT13 expression, in comparison to the matching normal squamous tissues, was found in oral dysplasia, squamous carcinomas and carcinoma in situ, esophageal squamous cell carcinoma, bladder cancer, lymph node-positive uterine cervix cancer, and head and neck squamous cell carcinoma cell lines." (PMID 27835867, 2016).
metastatic tumors (3 papers, 2016 to 2022). "Using three pairs of clinical specimens, we further confirmed the association between KRT13, PG, and c-Myc by mQDL, as both KRT13 and c-Myc levels were elevated, whereas both cytosolic and nuclear PG levels were lowered in metastatic tumors than in the primary tumor specimens." (PMID 35078507, 2022). "Evaluation of tumors/HGPIN in prostate biopsies from patients with metastatic disease consistently showed KRT13+ HGPIN lesions adjacent to tumor foci." (PMID 27711225, 2016). "When KRT13 overexpressing cells were injected intracardially, metastatic tumors were detected largely in bone and brain." (PMID 27835867, 2016).
adenocarcinoma of the prostate (2 papers, 2016 to 2022). "However, as we could show expression of KRT13 in the basal cells of benign glands, and since the loss of basal cells is one hallmark of prostate adenocarcinoma, lower expression levels in urine could also be explained by increased tumoral occupation of the gland." (PMID 35267445, 2022). "In comparison to adenocarcinoma of the prostate, breast, and lung, stronger KRT13 staining was observed in breast and lung cancer tissues with squamous histopathology (data not included)." (PMID 27835867, 2016).
Hyperkeratosis (2 papers, 2018 to 2020). Hyperkeratosis is a histopathological term defining a thickened stratum corneum and may be present in many different skin conditions, with many possible overlaps. "When these genetic mutations occur in the genes encoding KRT4 or KRT13, this leads to cell fragility in the oral and/or ano-genital mucosa, which presents as white “spongy” plaques reflecting underlying cell fragility, cytolysis and compensatory overgrowth (hyperkeratosis)." (PMID 29476668, 2018). "Failure of this structural scaffold within KRT4- and KRT13-expressing keratinocytes leads to epithelial fragility and hyperkeratosis in the oral and anogenital mucosa." (PMID 29476668, 2018).
lung carcinoma (2 papers, 2016 to 2023). "The significance of KRT13 and cancer bone and brain metastases was confirmed in clinical prostate, breast and lung cancer specimens." (PMID 27835867, 2016). "The level of KRT13 expression is equivalent to pathologic specimens of human prostate, breast, and lung cancers." (PMID 27835867, 2016).
metastatic cancer (2 papers, 2016 to 2020). A carcinoma which has spread from the original site of growth to another anatomic site. "Recently, cytokeratin (CK) 13 (KRT13) has been identified as a marker for normal human prostate epithelial stem/progenitor cells, as well as bone marrow metastatic cancer cells." (PMID 33318499, 2020).
papilloma (2 papers, 2004 to 2021). A benign epithelial neoplasm that projects above the surrounding epithelial surface and consists of villous or arborescent outgrowths of fibrovascular stroma. "Mcpip1eKO papillomas were characterized by elevated transcriptional expression of Krt5, Krt13 and keratin 14 (Krt14), indicating a highly proliferative phenotype." (PMID 34903245, 2021). "Moreover, we observed a transcriptional increase in Krt13 expression, which is characteristic of the progression of mouse papillomas into SCC." (PMID 34903245, 2021).
prostate tumor (2 papers, 2016). "In order to determine if KRT13 is expressed in PC, tissue specimens from radical prostatectomy specimens, diagnostic PNBX of primary prostate tumors, and PC bone metastases were collected and subjected to immunostaining." (PMID 27711225, 2016). "Interestingly, although KRT13 was discovered in TIC, which is a basal cell subpopulation, KRT13 expression in prostate tumors is associated with a luminal (PSA+ CK5- P63-) phenotype." (PMID 27711225, 2016).
urothelial carcinoma (2 papers, 2016 to 2022). A malignant neoplasm derived from the transitional epithelium of the urinary tract (urinary bladder, ureter, urethra, or renal pelvis). "These intermediate cells give rise to the luminal subtype of urothelial carcinoma and our results showed that expression of KRT13 mRNA in the RT4 cell line was low and treatment with As3+ further decreased the expression of this gene." (PMID 36293167, 2022).
bladder tumors (1 paper, 2010). "For four of these loci (FRZB, STAT5A, KRT13, and HOXB2), bisulfite pyrosequencing assays were able to be designed, and were used to confirm the array findings in a subset of bladder tumors examined on the array." (PMID 20808801, 2010). "Pyrosequencing of the promoter regions of FRZB, KRT13, and HOXB2 was performed in an independent series of 263 bladder tumor patients not examined on the array as well as on 4 non-diseased tumor samples obtained from the NDRI." (PMID 20808801, 2010).
breast tumours (1 paper, 2019). "For example, KRT13 had higher TAC mRNA abundance in HER2-enriched breast tumours." (PMID 31308365, 2019).
cervical tumor (1 paper, 2024). "KRT13 is a differentiation marker expressed in the upper cervical base that decreases with an increase in the degree of cervical tumor malignancy." (PMID 38229169, 2024).
cystitis (1 paper, 2023). Inflammation of the urinary bladder. "Krt6 and Krt13 has not been reported as a mediator of H2O2-induced cystitis." (PMID 37931000, 2023).
endometrial cancer (1 paper, 2023). Primary or metastatic malignant neoplasm involving the endometrium (mucous membrane that lines the endometrial cavity). "The incorporation of RTN4, LAMP2, WDR1, KRT13, ALDH2 and ILF3 gave rise to a ten-marker biomarker panel, which predicted endometrial cancer with an AUC of 0.91 (0.86–0.96), and was the best performing diagnostic model." (PMID 36807337, 2023).
esophageal carcinoma (1 paper, 2023). A primary or metastatic malignant neoplasm involving the esophagus. "However, KRT13 and KRT15 were found to be down-regulated in TCGA-derived esophageal carcinoma samples." (PMID 36949761, 2023).
head and neck cancer (1 paper, 2021). A primary or metastatic malignant neoplasm affecting the head and neck. "Several studies showed the association of KRT13 with multiple cancer types including prostate, head and neck cancer, urothelial cancer." (PMID 34795689, 2021).
oral cancers (1 paper, 2023). "Furthermore, the phylogenetically and semantically related KRT13 and KRT15 are also directly associated in oral cancers." (PMID 36949761, 2023).
ovarian carcinoma (1 paper, 2010). A malignant neoplasm originating from the surface ovarian epithelium. "We identified TF encoding genes that were putatively controlled by PEs common to the keratin group (KRT8, KRT13, KRT18), and are also previously reported to be at least 5-fold over-expressed in early and late stage ovarian cancer." (PMID 20181230, 2010).
pancreatic cancer (1 paper, 2023). "Database analysis revealed that KRT13 is highly expressed in pancreatic cancer cell lines and that high expression of KRT13 is associated with poorer prognosis." (PMID 36610719, 2023). "Furthermore, TCGA survival data showed that high KRT13 expression is associated with poor prognosis in patients with pancreatic cancer (P < 0.0001)." (PMID 36610719, 2023). "Furthermore, a database search revealed that KRT13 is upregulated in pancreatic cancer cell lines and that high expression of KRT13 is associated with poorer prognosis." (PMID 36610719, 2023). "Although further investigation is required, the combination therapy of sCA-siRNA for KRT13 and radiation may be a promising therapeutic approach in pancreatic cancer." (PMID 36610719, 2023). "Taken together, these results suggest that KRT13 knockdown in combination with radiotherapy could be a new strategy for treating pancreatic cancer." (PMID 36610719, 2023). "Our results indicate that a combination therapy of KRT13 knockdown and radiation could be an effective strategy in pancreatic cancer." (PMID 36610719, 2023).
prostatic intraepithelial neoplasia (1 paper, 2016). "Strong KRT13 expression was observed in high-grade prostatic intraepithelial neoplasia (HGPIN) lesions, although adjacent cancers rarely expressed KRT13." (PMID 27711225, 2016).
staphylococcus aureus infection (1 paper, 2024). An infectious process in which the bacteria Staphylococcus aureus is present. "Notably, Staphylococcus aureus infection was identified as one of the key pathways in which Cluster35 participated, due to its influence on several Keratin-related genes, such as KRT13, KRT23, and KRT27." (PMID 38448858, 2024).
vitamin A deficiency (1 paper, 2025). Deficiency of vitamin A due to malnutrition, malabsorption, or dietary lack. "A subpopulation of Krt13+ cells localized to discrete sites of the tracheal epithelium named ‘hillocks’ has been recently shown to be a source of vitamin A deficiency-induced murine squamous metaplasia." (PMID 40310937, 2025).